INS (insulin)
Diseases named in the same sentence as INS in open-access papers (continued):
Sharing a sentence is not in itself a finding about the gene and the disease.
Insulin resistance (continued). "Taken together, the evidence shows that long sleep duration increases inflammatory cytokines and insulin resistance, and poor sleep quality also increases inflammatory cytokines and decreases insulin sensitivity; these factors all increase stroke risk." (PMID 32457400, 2020). "Overnutrition induced by short-term overfeeding in mice rapidly causes onset of cellular insulin resistance in adipocytes, marked by impaired insulin signaling at the level of insulin receptor substrate (IRS)-1 and Akt." (PMID 33021706, 2020). "The augmentation of ROS has been shown to activate c-jun N terminal kinase 1 (JNK1), which is implicated in obesity-induced insulin resistance and decreased compensatory insulin secretion, both of which are key features of type 2 diabetes." (PMID 32575419, 2020). "Some studies have also reported that tai chi can consume heat energy and promote the decomposition of sugar, which is conducive to weight loss in obese patients with T2DM and can reduce insulin resistance and increase insulin sensitivity." (PMID 33332396, 2020). "A recent study comparing insulin profiles in two high-risk ethnic groups found a higher propensity for insulin resistance, as measured by HOMA-IR, among Pima Indians compared with Asian Indians, who had substantially lower insulin secretion." (PMID 31973762, 2020). "Abundant evidence indicates that adiposity and adipose tissue inflammation are associated with insulin resistance, which refers to a reduced response to binding of insulin to its receptor in peripheral tissues such as adipose tissue and skeletal muscle." (PMID 32158768, 2020). "Some recently-identified miRNAs have been associated with insulin secretion, insulin resistance, and inflammation, and differences have emerged in some circulating miRNA levels between individuals with and without type 2 diabetes." (PMID 33335512, 2020). "An increase in blood viscosity will cause a decrease in blood flow rate, which can cause a decrease in the amount of insulin that can bind to its receptors in the tissue and is associated with insulin resistance." (PMID 33281368, 2020). "A greater increase in leg length between generations was associated with lower fasting insulin and insulin resistance." (PMID 33033015, 2020). "Type 2 diabetes (T2D) is caused by progressive loss of insulin secretion from β-cells and/or insulin resistance." (PMID 32727064, 2020). "Defective insulin signaling associated with insulin resistance and response to PTH or PTHrP are involved in the activation of a proinflammatory response and the release of cytokines." (PMID 32751307, 2020). "As an insulin sensitizer, metformin was originally used to treat insulin resistance associated with PCOS." (PMID 32660613, 2020). "Accordingly, the purpose of the study was to examine the impact of succinic acid on body weight, adiposity, insulin action, and mitochondrial function in high‐fat diet‐induced obesity, and associated insulin resistance, in C57/Bl6 male mice." (PMID 33185326, 2020). "A logistic regression model was employed to explore the associations of SNPs with insulin resistance and impaired insulin release by correcting for the confounders." (PMID 32260174, 2020). "Systemic insulin resistance triggers chronic hyperglycemia, which causes pancreatic β cells to secrete more insulin." (PMID 32899870, 2020). "Given the major role of skeletal muscle in regulating systemic carbohydrate metabolism and insulin signalling, key genes and proteins implicated in insulin resistance were investigated." (PMID 31968625, 2020). "An increase in insulin resistance, caused by smoking, will also affect the overall impact and hence the usage of inhaled insulin." (PMID 32850233, 2020). "The adipose tissue plays a central role in insulin sensitivity and energy expenditure, and the dysfunction in adipocytes is associated with insulin resistance and type 2 DM (T2DM)." (PMID 32047529, 2020).
Insulin resistance (continued). "Obesity was said to be associated with insulin resistance, and one of the factors that influence the insulin secretion is the blood glucose level and the expression of dipeptidyl-peptidase 4 (DPPIV) protein, which involves in the glucose metabolism." (PMID 33029159, 2020). "The placenta produces hormones that play roles in fetal growth, but these hormones also affect maternal insulin levels, which causes insulin resistance and increased insulin secretion." (PMID 32984349, 2020). "It has been shown that the association between IMCL accumulation and insulin resistance can be mechanistically explained by the interference of lipid intermediates with insulin signalling." (PMID 32185462, 2020). "Failure of insulin to inhibit hepatic glucose output and gluconeogenesis is the hallmark of hepatic insulin resistance." (PMID 32455838, 2020). "Insulin resistance leads to increased levels of insulin and its associated growth factors, in particular insulin-like growth factor 1 (IGF-1), and the development of type 2 diabetes." (PMID 32630445, 2020). "Normalization of circulatory adipokines and activation of the PI3K/Akt insulin signal cascade in skeletal muscle was found to be the underlying mechanism for Pt-PS-alleviated insulin resistance." (PMID 32971772, 2020). "Integration of genetic and metabolomics data in the present study demonstrated that one metabolite associated with maternal insulin sensitivity, palmitoleic acid, mediates, in part, the association of a genetic variant with insulin resistance." (PMID 32556615, 2020). "Although it is well-known that metabolic disorders (such as insulin resistance, T2D and/or obesity) increase the risk for AD, the opposite (i.e., AD-induced peripheral glucose dysmetabolism and insulin insensitivity) remains a matter of debate." (PMID 32143329, 2020). "Metformin is an antidiabetic drug that is not only a first choice treatment of type 2 diabetes mellitus but because of its proven insulin-sensitizing properties has been also widely used in other conditions associated with insulin resistance, including PCOS." (PMID 33260918, 2020). "The REE was also strongly associated with BMI (p < 0.00001), leptin (p < 0.001), insulin concentration (p < 0.001), and insulin resistance (p < 0.001)." (PMID 32651404, 2020). "Regarding insulin sensitivity, previous studies have shown that early postnatal overnutrition in rats is associated with insulin resistance, both peripherally and centrally." (PMID 32093229, 2020). "Insulin resistance is associated with the inability of target tissues to increase glucose uptake in response to insulin." (PMID 32121669, 2020). "Incontrast, T2DM is caused by obesity-induced insulin resistance associated with arelative decrease in insulin secretion." (PMID 31479096, 2020). "This disorder is caused by the body’s inability to use insulin to process glucose (i.e., insulin resistance)." (PMID 33228030, 2020). "The higher amount of hepatic and visceral adipose tissue in men has been linked to higher insulin resistance, with women more sensitive to insulin partially due to estrogen." (PMID 33143284, 2020). "Recently, it was described that CB increased activity is associated with increased circulating insulin levels and insulin resistance evaluated by HOMA-IR." (PMID 33353562, 2020). "Insulin resistance associated with obesity indicates a decrease in the body’s ability to activate the insulin signaling pathway, which stimulates glucose uptake and metabolism." (PMID 33841133, 2020). "Insulin resistance, a hallmark of obesity and type 2 diabetes, is characterized by the defect of insulin to stimulate glucose uptake and utilization in the liver, skeletal muscles and adipose tissues." (PMID 33062046, 2020). "These processes can impair skeletal muscle insulin sensitivity and increase the risk of insulin resistance and type 2 diabetes during the skeletal muscle aging process." (PMID 32082422, 2020).
Insulin resistance (continued). "It is characterized by hyperglycemia due to the insufficient secretion of insulin, caused by a dysfunction of insulin-secreting pancreatic β cells, and decreased insulin sensitivity, caused by insulin resistance." (PMID 32724824, 2020). "It has been demonstrated that mice with GPR43 gene knockout presented an obese phenotype, excessive accumulation of fat, and predisposition to obstacles of insulin signal transmission, thus inducing insulin resistance." (PMID 33817264, 2020). "Our study aimed to integrate maternal metabolic and genetic data related to insulin sensitivity during pregnancy to provide novel insights into mechanisms underlying pregnancy-induced insulin resistance." (PMID 32556615, 2020). "There are several studies that suggest that high insulin concentrations are associated with typical pathologies of the metabolic syndrome, such as insulin resistance, obesity, hypertension, cardiovascular diseases, atherosclerosis, and hepatic steatosis." (PMID 32283715, 2020). "Treatment with Ga reproducibly decreased hepatic TG contents and attenuated insulin resistance, causing significant reductions in blood levels of glucose, insulin and leptin." (PMID 32792584, 2020). "This association between CNS and peripheral insulin resistance demonstrates the rationale for exploring insulin‐sensitizing drugs, such as those used for type 2 diabetes." (PMID 32704569, 2020). "Though hyperinsulinemia is a hallmark of insulin resistance in db/db mice, at the end point, the highest fasting insulin concentration was in DB/H group, with significant differences from DB/L and DB groups." (PMID 33312555, 2020). "Type 2 diabetes mellitus (T2DM) is a metabolic disease caused by impaired insulin secretion or insulin resistance, which induces glucose, fat, and protein metabolism disorders in the body." (PMID 33134394, 2020). "To further investigate this finding, we next explored the causal relationship between obesity and systemic insulin resistance (i.e. decreased insulin sensitivity assessed by the Matsuda index) in the METSIM cohort." (PMID 32925908, 2020). "We investigated the association between insulin resistance, serum adiponectin, insulin, and leptin with hepatic steatosis in a cohort of liver transplant recipients." (PMID 32728230, 2020). "Obese Zucker rats represent a well-known model of the prediabetic state characterized by peripheral insulin resistance, which is caused by an impaired insulin-stimulated glucose uptake in skeletal muscle." (PMID 32089774, 2020). "The negative correlation between Trunk-LL-fat ratio and total and HMW adiponectin levels, which is known to play an insulin sensitizing role, is a possible mechanistic explanation for the association between excess global trunk fat and insulin resistance." (PMID 33163464, 2020). "Myocardial insulin resistance is a cause for HF due to defective glucose utilization and insulin-dependent cell survival." (PMID 32223896, 2020). "Insulin resistance (IR) is an important disorder in patients with polycystic ovary because of the association between inflammatory and insulin signaling pathways." (PMID 32405346, 2020). "Overweight and obesity have been associated with inflammation, oxidative stress, and insulin resistance, as well as with changes in the levels of various bioactive compounds, e.g., lipids, insulin, leptin, adipokines, and some cytokines." (PMID 32599847, 2020). "Considering high prevalence rates of metabolic diseases linked by insulin resistance, we performed a systematic review of existing literature which addressed the role of probiotics in modulating insulin sensitivity in animals and humans." (PMID 33292434, 2020). "Type 1 DM is caused by destruction of the insulin producing pancreatic β-cell islet while insulin resistance is the main cause for type 2 DM." (PMID 33255372, 2020).
Insulin resistance (continued). "Activation of PKC isoforms by DAG accumulation in insulin-sensitive tissues has been linked to insulin resistance in obesity, and in mouse liver, lipin 1 mediated DAG production led to insulin resistance via activation of PKCε." (PMID 33003344, 2020). "Elevated leptin during obesity is a known risk factor and contributor to insulin resistance and glucose intolerance by suppressing proinsulin synthesis and insulin secretion." (PMID 31947955, 2020). "Both type 1 and type 2 diabetes have in common hyperglycemia and deficient insulin‐dependent signaling because of low insulin levels (type 1) or insulin resistance commonly associated with obesity (type 2)." (PMID 32666590, 2020). "Individuals carrying risk alleles predisposed to T2D are mediated by insulin resistance or abnormal insulin secretion." (PMID 32260174, 2020). "PTP1β is a protein that negatively regulates the insulin signaling pathway and can cause insulin resistance." (PMID 33192493, 2020). "Sphingolipid dysregulation is often associated with insulin resistance, while the enzymes controlling sphingolipid metabolism are emerging as therapeutic targets for improving insulin sensitivity." (PMID 32917816, 2020). "Insulin resistance and type 2 diabetes are associated with impaired insulin-stimulated glucose uptake in skeletal muscle and adipose tissue." (PMID 32591906, 2020). "The decrease in insulin sensitivity, pancreatic β-cell function, and insulin synthesis and secretion caused by low vitamin D level is related to insulin resistance." (PMID 32149047, 2020). "Parental height was unrelated to offspring CVD risk factors; however, a greater intergenerational increase in leg length was associated with lower insulin and insulin resistance." (PMID 33033015, 2020). "In humans, visceral adipose tissue is associated with insulin resistance, dyslipidaemia and Type 2 diabetes, while subcutaneous adipose tissue is associated with preserved insulin sensitivity and mitigates risk of metabolic disorders." (PMID 32785142, 2020). "Angiotensin II can cause insulin resistance by interfering with the insulin-stimulated increase in insulin receptor substrate 1-associated PI3K activity." (PMID 33240326, 2020). "Regarding ectopic fat accumulation, adipose depots located in major glucose-regulatory organs such as the liver, skeletal muscle, and pancreas usually deregulate insulin signalling, promoting insulin resistance and increasing the risk for T2DM and CVDs." (PMID 33081064, 2020). "Insulin resistance is a common phenomenon, closely associated with obesity, and defined as the inability of target tissues to respond normally to insulin." (PMID 32365816, 2020). "Growing evidence suggests that this enhanced degree of low-grade systemic inflammation is an important factor leading to the insulin secretion defects and uncompensated insulin resistance underlying impaired gestational glucose metabolism." (PMID 32093765, 2020). "Obesity is among the risk factors for decreased insulin sensitivity or increased insulin resistance, defined as the decreased response of a nutrient to a given concentration of insulin at target tissue such as liver, muscle, or adipose tissue." (PMID 32455565, 2020). "A decrease in the adiponectin secretion has been associated with insulin resistance in mouse models of altered insulin sensitivity." (PMID 33191653, 2020). "Weight gain typically causes insulin resistance, i.e., hampers the ability of insulin to enhance glucose utilization and suppress glucose production." (PMID 33324238, 2020). "The classic view held that the antagonistic effects of prolactin, prolactin, glucocorticoid, and progesterone on insulin secretion and insulin resistance during pregnancy were the main causes of GDM." (PMID 32280713, 2020).
Insulin resistance (continued). "A positive correlation has been observed between insulin sensitivity and adiponectin levels both in vitro and in vivo; thus, decreased blood adiponectin levels should be associated with increased insulin resistance." (PMID 33224988, 2020). "This suggests that observed association between sclerostin levels and insulin resistance can indirectly reflect the deteriorative effect of higher BMI on insulin sensitivity." (PMID 32592042, 2020). "Studies have shown that the expression of the FKBP5 gene is positively correlated with serum insulin and is associated with insulin resistance." (PMID 32281722, 2020). "In patients with polycystic ovary syndrome and insulin resistance, pioglitazone-induced improvement of insulin action is associated with an increase in muscle ApoJ and LRP2 expression." (PMID 32332780, 2020). "Two mechanisms underlying T2DM are insulin resistance and insufficient insulin secretion from pancreatic β-cells." (PMID 32139775, 2020). "Nevertheless, even if glucose and insulin metabolism show an increased risk of insulin resistance, HbA1c levels are usually normal in most SMA patients examined." (PMID 33339220, 2020). "Type 2 diabetes is a metabolic disease characterized by insulin resistance and/or abnormal insulin secretion that is caused by multiple factors including genetics, nutrition, and physical activity." (PMID 33042976, 2020). "Despite the growing body of literature highlighting various aspects of insulin signaling impairment leading to insulin resistance, the underlying molecular mechanisms are yet to be fully understood." (PMID 33038072, 2020). "Experimental findings have indicated that the elevated blood urea nitrogen level causes insulin resistance and diminishes insulin secretion." (PMID 32143382, 2020). "Since NAFLD is often associated with insulin resistance, intraperitoneal glucose-, and insulin-tolerance tests were conducted." (PMID 33013934, 2020). "Numerous studies demonstrated the association of increased oxidative stress and insulin resistance pathogenesis mediated by insulin signal inhibition and adipokines dysregulation." (PMID 32405361, 2020). "Still, insulin-resistant and insulin-deficient rats benefit from oral CAPE administration (30 mg/kg/day) as it ameliorates the rise in blood pressure, an effect attributed to CAPE-mediated improvement of vascular reactivity and stiffness." (PMID 33343392, 2020). "This multifactorial disease is characterized by hyperglycemia, insulin deficiency, insulin resistance, and/or abnormal insulin secretion." (PMID 32878147, 2020). "There are significant differences between women and men in the role of insulin, susceptibility to insulin resistance, and response to stimuli." (PMID 32280714, 2020). "The ATTICA study described that adherence to the Mediterranean diet was linked to improved fasting glucose homeostasis, insulin levels, and a better insulin resistance index (HOMA) in both normoglycemic individuals and diabetic participants." (PMID 32726990, 2020). "There are many factors that cause insulin resistance, including dysfunctional binding to insulin receptor, abnormal insulin secretion, lipid oversupply and alterations in substrate metabolism." (PMID 32982723, 2020). "Contrary to the assumption that insulin resistance is the main driver of glucocorticoid-induced hyperglycemia, results indicate that decreased beta-cell insulin secretion is the more likely cause in those with T2DM." (PMID 32369480, 2020). "Numerous studies established that oxidative stress is implicated in the development of insulin resistance via inhibition of insulin signals and adipokines dysregulation." (PMID 33335883, 2020). "In acute conditions, GCs act on the pancreas and stimulate secretion of insulin that exerts an inhibitory role on food intake, whereas chronic exposure to GCs leads to insulin resistance, i.e. the loss of insulin’s ability to inhibit NPY/AgRP in ARC." (PMID 32272767, 2020).